SIRT3 (sirtuin 3)
Diseases named in the same sentence as SIRT3 in open-access papers (continued):
Sharing a sentence is not in itself a finding about the gene and the disease.
Hypertension (continued). "Administration of alpha-linolenic acid (ALA) restores endothelial cell autophagic flux and mitochondrial redox stress via increased SIRT3 activity, which improves endothelial cell dysfunction and attenuates experimental hypertension." (PMID 37237500, 2023). "Collectively, these findings suggest that reduced SIRT3 expression triggered by hypertension results in VSMC activation, leading to increased extracellular matrix secretion and vascular remodeling." (PMID 37237500, 2023). "Patients with hypertension have decreased Sirt3 expression leading to hyperacetylation of mitochondrial proteins." (PMID 36675125, 2023). "This review highlights recent advances in the biological function and structure of SIRT3, and the metabolic mechanisms by which SIRT3 mediates cardiovascular remodeling in the context of hypertension." (PMID 37237500, 2023). "Ecklonia cava extract (ECE) decreases hypertension-related vascular calcification through SOD2 SIRT3-deacetylation." (PMID 37237500, 2023). "An earlier study had shown that SIRT3 depletion during hypertension increases vascular oxidative stress, promotes endothelial dysfunction, vascular inflammation, and end-organ damage." (PMID 36211825, 2022). "SIRT3 also represses stress-induced hypertension by regulating MnSOD hypoacetylation and ROS homeostasis in endothelial cells and by repressing endothelial-to-mesenchymal transition." (PMID 35855341, 2022). "The heart mass ratio (heart weight / body weight) was increased in hypertension mice than controls, and after Ang II infusion, the heart mass ratio of SIRT3‐KO mice was higher than that of WT mice." (PMID 34180125, 2021). "Western blot and RT‐PCR demonstrated that the mRNA and protein level of VEGFR3 and LYVE1 were down‐regulated in heart of hypertension mice compared with saline group, and SIRT3‐KO further down‐regulated the mRNA and protein expression in hypertension model." (PMID 34180125, 2021). "This suggests that SIRT3 deficiency leads to SOD2 hyperacetylation and elevated ROS, which contribute to hypertension." (PMID 33499277, 2021). "Western blot showed that MYH6 protein levels were elevated in hypertension mice compared in control mice, and SIRT3‐KO up‐regulated the expression of MYH6 compared with WT group." (PMID 34180125, 2021). "SIRT3 has also been shown to blunt hypertension-induced renal injury via suppression of the endothelial-to-mesenchymal transition." (PMID 33371209, 2020). "More interestingly, SIRT3 KO mice developed severe hypertension in response to a low dose of AngII infusion, while ALA supplementation lost its anti-hypertensive and endothelium-protective effects on these mice." (PMID 32015327, 2020). "Clinical studies have revealed that SIRT3 expression decreases by 40% by 65 years of age45, which is paralleled with the increased incidence of hypertension." (PMID 32015327, 2020). "SIRT3 knockout rendered the mice more susceptible to AngII-induced hypertension and abolished the endothelium-beneficial and antihypertensive effects of ALA supplementation, indicating the critical role of SIRT3 in vascular protective effects of ALA." (PMID 32015327, 2020). "Previous data from other labs as well as ours have shown that SIRT3 deficiency and resultant SOD2 hyperacetylation and mitochondrial ROS overproduction contribute to the development of hypertension and vascular dysfunction in obesity." (PMID 32015327, 2020). "Mitochondrial oxidative stress–induced endothelial dysfunction in hypertension has been attributed to reduced sirtuin 3 (SIRT3)–mediated superoxide dismutase 2 (SOD2) signalling." (PMID 32389339, 2020). "Our findings suggest that ALA but not LA supplementation improves endothelial dysfunction and diminishes experimental hypertension by rescuing SIRT3 impairment to restore autophagic flux and mitochondrial redox balance in endothelial cells." (PMID 32015327, 2020).
Hypertension (continued). "In the present study, we aim to investigate the functional roles of SIRT3 in cardiac fibrosis in response to hypertension." (PMID 32463172, 2020). "Changes in SOD2 expression and Sirt3 were also present in adult rats that developed hypertension after having ingested sucrose during the critical window." (PMID 30717220, 2019). "Emerging evidence indicates that exercise can decrease oxidative stress and we believe that exercise-induced activation of SIRT3 is a key step of this defense in the condition of hypertension." (PMID 31116256, 2019). "In animal models of hypertension, cardiac disease and ischemic stroke, Sirt3 has shown to suppress oxidative stress by regulating NOX2, NOX4, SOD2, Nrf2 and FoxO3a." (PMID 30362958, 2018). "a-linolenic acid may improve endothelial function and alleviate hypertension by counteracting the decline of SIRT3 function, to restore autophagy and mitochondrial redox balance in endothelial cells." (PMID 40507062, 2025). "SIRT3 expression is significantly decreased in the arterioles of patients with hypertension, and transgenic mice overexpressing SIRT3 exhibited a reversal of hypertension, endothelial dysfunction, and vascular oxidative stress." (PMID 39564112, 2024). "additionally observed reduced SIRT3 expression in a murine model of hypertension." (PMID 39911234, 2024). "Besides, PINK1/Parkin was demonstrated as the potential substrate of SIRT3, for their acetylation increased in response to hypertension-related cardiac remodeling and SIRT3 overexpression restore the mitophagy and angiogenesis." (PMID 39464632, 2024). "Consequently, SIRT3 is an attractive therapeutic target to improve metabolic abnormalities in hypertension." (PMID 37237500, 2023). "Here, we examine the potential roles of SIRT3 in cardiovascular remodeling in hypertension." (PMID 37237500, 2023). "Sirt3 gene deletion in mice promotes vascular dysfunction and hypertension." (PMID 36675125, 2023). "In contrast, global SIRT3 overexpression blocks Ang II-induced hypertension." (PMID 38020895, 2023). "SIRT3 depletion causes hyperacetylation of mitochondrial SOD2 and overproduction of oxidative stress, which results in endothelial dysfunction, vascular inflammation, and hypertension in mice." (PMID 37143582, 2023). "Furthermore, genetic deletion of SIRT3 in mice leads to hypertension by inducing endothelial dysfunction, vascular inflammation, and hypertrophy." (PMID 38020895, 2023). "SIRT3 was shown to play a role in hypertension and pulmonary arterial hypertension (PAH)." (PMID 35855341, 2022). "Similarly, SIRT3 loss leads to high acetylation of mitochondrial SOD2, leading to endothelial dysfunction, hypertension, and other cardiovascular diseases in mice." (PMID 35855865, 2022). "Further studies are ongoing to test whether genetic deletion of mitochondrial SIRT3 in the proximal tubules of the kidney aggravates Ang II-induced hypertension by impairing the pressure-natriuretic response and inducing Na+ retention in PT-SIRT3−/− mice." (PMID 34408663, 2021). "SIRT3 and lymphangiogenesis may represent a new therapeutic target for the attenuation of hypertension and cardiac remodelling." (PMID 34180125, 2021). "The regulation of SIRT3 on mitochondrial ROS scavengers is important under different experimental mice models that stimulate endothelial cells, as evident in angiotensin II-induced hypertension model or cardiovascular inflammation." (PMID 34712151, 2021). "We have recently tested the hypothesis that genetic deletion of SIRT3 selectively in the proximal tubules of the kidney aggravates Ang II-induced hypertension in proximal tubule-specific SIRT3 knockout mice, PT-SIRT3−/−." (PMID 34408663, 2021). "Furthermore, deletion of SIRT3 selectively in the proximal tubules of the kidney significantly augmented Ang II-induced hypertension in PT-SIRT3−/− mice." (PMID 34408663, 2021).
Hypertension (continued). "In preliminary antihypertensive mechanism, metformin may contribute to remission of hypertension through activating sirtuin 3/AMP-activated protein kinase (SIRT3-AMPK) signaling pathway." (PMID 34334083, 2021). "SIRT3 may suppress inflammasome assembly during fasting, and SIRT3 overexpression reversed the inflammatory cytokine expression in a hypertension model or macrophage stimulation in mice." (PMID 34712151, 2021). "Although both SIRT3 and pericytes play a crucial role in fibrosis, the association between these two in hypertension‐induced cardiac fibrosis has not been defined." (PMID 32463172, 2020). "Our data demonstrate that endothelial SIRT3 reduction is concomitant with dysregulation of autophagic flux in endothelial cells of hypertension, and both could be rescued by ALA administration." (PMID 32015327, 2020). "Furthermore, SIRT3-knockout mice aggravated hypertension-induced renal dysfunction and renal fibrosis via chronic AngII infusion (2000 ng/kg per minute for 42 days)." (PMID 28465484, 2017). "In experimental studies, SIRT3 expression has been regulated by Angiotensin II, which may play a pivotal role in the etiology of hypertension." (PMID 22087257, 2011). "However, SIRT3 KO mice developed severe hypertension to 180 mmHg in response to low-dose AngII (0.4 mg/kg/d, 2 weeks) infusion, while AngII (0.4 mg/kg/d, 2 weeks) infusion increased SBP of WT mice to 143 mmHg as measured by carotid artery catheterization method." (PMID 32015327, 2020). "Recent studies have shown that SIRT3 activation could alleviate the development of mouse hypertensive renal fibrosis by the suppression of endothelial-to-mesenchymal transition and that the activation of SIRT3 signaling could ameliorate mouse injury induced by hypertension." (PMID 33233553, 2020). "During hypertension, SIRT4 acts as a negative regulator of SIRT3, thereby suppressing SIRT3-mediated mitophagy and inhibiting the deacetylation of manganese superoxide dismutase (MnSOD) at K122 residue." (PMID 40705152, 2025). "Preventing hypertension and controlling blood pressure depend heavily on the T3-THRA1/PGC-1α/SIRT3 cascade." (PMID 41567643, 2025). "For example, SIRT3 depletion in SIRT3-/- mice results in oxidative stress, endothelial dysfunction, and hypertension due to the hyperacetylation of mitochondrial SOD2, whereas increasing SIRT3 expression reverses these effects." (PMID 37196115, 2023). "One study found that diminished Sirt3 expression significantly increased mtROS production due to SOD2 acetylation, which promotes the development of hypertension." (PMID 35769207, 2022). "Moreover, SIRT3, an important regulator of mitochondrial antioxidant defense mechanism, scavenged mitoROS by stimulating deacetylation of superoxide dismutase 2, thus improving mitochondrial oxidative stress damage including essential hypertension, cardiac fibrosis, and diabetic cardiomyopathy." (PMID 36192726, 2022). "Western blot showed that α‐SMA protein levels were elevated in heart of hypertension mice compared with control, with further up‐regulated expression of α‐SMA in SIRT3‐KO mice." (PMID 34180125, 2021). "In the present study, we found that Ang II‐induced hypertension inhibited lymphangiogenesis and down‐regulate the expression of lymphatic markers in mice hearts and decrease VEGFC in their serum, and SIRT3‐KO further suppressed these processes." (PMID 34180125, 2021). "Sirtuin 3 (SIRT3), a mitochondrial nicotinamide adenine dinucleotide (NAD)+-dependent deacetylase, plays a key role in hypertension-induced renal injury." (PMID 33233553, 2020). "We also studied the expression of Sirt1, which regulates eNOS expression and Sirt3, which regulates SOD2 expression as possible epigenetic targets of enzyme expression involved in the long- term programming of hypertension." (PMID 30717220, 2019). "Previous studies have shown that the absence of SIRT3 results in vascular dysfunction and hypertension." (PMID 40622073, 2025).
Hypertension (continued). "Besides, SIRT3 depletion can induce mitochondrial damage due to SOD2 acetylation and SOD2 inactivation in vascular dysfunction and hypertension." (PMID 39300372, 2024). "The absence of sirtuin-3 can precipitate the onset of hypertension and stimulate the progression of cardiac fibrosis, a condition characterized by excess fibrous connective tissue in the heart." (PMID 37955687, 2023). "Sirtuin 3 (SIRT3) is an effective mitochondrial deacetylase that has the potential to modulate this process; however, its role in hypertension‐induced cardiac lymphangiogenesis to date has not been investigated." (PMID 34180125, 2021). "The suggestion is based on observations of reduced SIRT3 expression in the lungs of old mice and two murine models of fibrosis, and spontaneous arterial hypertension and cardiac fibrosis observed in mice lacking SIRT3." (PMID 31011489, 2019). "Complementary findings in essential hypertension indicate that vascular SIRT3 depletion is accompanied by SOD2 hyper-acetylation, heightened oxidative stress, endothelial inflammation, and vascular remodeling, while SIRT3 overexpression reverses these phenotypes." (PMID 41465170, 2025). "However, the roles of mitochondrial SIRT3 in the proximal tubules in Ang II-induced hypertension and renal injury have not been investigated using mouse model with proximal tubule-specific knockout of SIRT3." (PMID 34408663, 2021). "However, the role of endothelial SIRT3 on hypertension in females has not been studied." (PMID 33371209, 2020). "The purpose of this study was to examine age-related expression patterns of these signaling molecules, in particular MT, SIRT1, SIRT3, and SIRT6 in BE of subjects of different ages with and without arterial hypertension (AH)." (PMID 33143333, 2020). "Our findings suggest that ALA but not LA supplementation rescues SIRT3 reduction, improves endothelial dysfunction and reduces blood pressure elevation in hypertensive animals, thus providing the proof of principle for the benefits of dietary ALA intake against hypertension." (PMID 32015327, 2020).
acute kidney injury (64 papers, 2015 to 2026). Sudden and sustained deterioration of the kidney function characterized by decreased glomerular filtration rate, increased serum creatinine or oliguria. "For example, in a cisplatin-induced acute kidney injury model, the reduction of SIRT3 mRNA and protein expression is associated with a marked mitochondrial accumulation of DRP1, severe mitochondrial damage and severe injury than WT animals." (PMID 32722183, 2020). "A recent study showed that ioversol treatment significantly increased the Sirt3 expression in wild-type (WT) mice and HK-2 cells, while Sirt3 deficiency aggravated the contrast-induced acute kidney injury." (PMID 31929854, 2019). "Indeed, mice with global deficiency of Sirt3 developed a more severe disease in an experimental mouse model of acute kidney injury (AKI) induced by cisplatin." (PMID 37816025, 2023). "A recent study demonstrated that SIRT3 deficiency aggravated contrast-induced acute kidney injury." (PMID 36714147, 2022). "Altogether, Sirt3 deficiency may aggravate oxidative stress in contrast-induced acute kidney injury." (PMID 30445987, 2018). "Our results suggest that Sirt3 deficiency aggravates contrast-induced acute kidney injury." (PMID 30445987, 2018). "The covalent binding of SUMO1 and Sirt3 increases during acute kidney injury (AKI), and the mutation of lysine to arginine significantly attenuates AKI while minimizing fibroblast-induced repair in a genetically modified mouse model." (PMID 39697538, 2024). "In cisplatin-induced acute kidney injury, mitochondrial SIRT3 decreases, resulting in increased acetylation levels of DHODH." (PMID 41513612, 2026). "In cadmium-induced acute kidney injury, the expression of SIRT3 declines, leading to a high level of acetylation modification of GPX4." (PMID 41513612, 2026). "In the kidneys, Sirt3 is thought to be a master regulator of protection against acute kidney injury, and its increase is important for improving mitochondrial dynamics." (PMID 39907422, 2025). "For instance, melatonin can mitigate sepsis-induced acute kidney injury by promoting mitochondrial autophagy through SIRT3-mediated deacetylation of mitochondrial transcription factor A (TFAM)." (PMID 39544947, 2024). "Recent studies have highlighted the renoprotective function of SIRT3 in cisplatin-induced acute kidney injury through its regulation of mitochondrial dysfunction." (PMID 39911234, 2024). "An important regulator of mitochondrial function, SIRT3 participates in the injury and repair processes of acute kidney injury (AKI)." (PMID 38294557, 2024). "Morigi M’s study demonstrated that the activation of SIRT3 can alleviate mitochondrial dysfunction in cisplatin-induced acute kidney injury." (PMID 39655278, 2024). "Recent studies have shown that Sirtuin 3 (SIRT3) is involved in the FAO regulation of cisplatin‐induced acute kidney injury." (PMID 35560773, 2022). "Melatonin relieves contrast-induced acute kidney injury by activating SIRT3 and diminishing ac-SOD2 K68, thus exerting an antioxidative effect." (PMID 35372451, 2022). "RNLS protects renal epithelial cells in cisplatin-induced Acute Kidney Injury by promoting mitochondrial dynamics and inhibiting ROS production in a Sirt3-dependent manner." (PMID 35898283, 2022). "The protective role of SIRT3 against mitochondrial damage in acute kidney injury (AKI) with the murine sepsis model is reported." (PMID 35052507, 2021). "In a mouse model of acute kidney injury, SIRT3 reduced Ac-SOD2 and ROS levels and attenuated oxidative damage, thereby resisting apoptosis." (PMID 34869361, 2021). "Sirtuin 3 (Sirt3) has been confirmed to alleviate acute kidney injury (AKI) by improving mitochondrial function and participate in the regulation of FAO in other disease models." (PMID 32281286, 2020). "It was reported that Silybin can improve kidney mitochondrial function via activating SIRT3 in a mouse model of cisplatin-induced acute kidney injury." (PMID 32724473, 2020).